ACTA2 (actin alpha 2, smooth muscle)
Diseases named in the same sentence as ACTA2 in open-access papers (continued):
Sharing a sentence is not in itself a finding about the gene and the disease.
tumor (continued). "Interestingly, the compatibility of somatic mutations between the two tumor sites did not exceed 1%, while overly expressed ACTA2 molecules were deemed responsible for the early incidence of metastasis in this patient." (PMID 38539567, 2024). "Interestingly, both CD8+ T and NK cells were also in close proximity to the CXCL12+ACTA2+ tumor area in high-stromal samples, which suggested that CXCL12 could keep CD8+ T and NK cells from trafficking into the tumor islets." (PMID 38182756, 2024). "We next investigated whether ACTA2 was also involved in HKDC1-mediated tumor immune escape." (PMID 38351096, 2024). "To explore this hypothesis, we investigated the relationship between tumor-stroma interaction as quantified by our model and the expression of the stromal markers ACTA2 — using α-smooth muscle actin (αSMA), a marker for activated fibroblast — and PECAM1 — using CD31, a marker for angiogenesis." (PMID 36647832, 2023). "Compared with NE-4C cells, the tumor showed a general tendency of upregulation of a series of genes representing neural stemness, genes representing neuronal differentiation, and genes representing mesodermal (Acta2, T, Desmin, Kdr) and endodermal tissue (Afp, Foxa2) differentiation." (PMID 33468253, 2021). "Therefore, we examined the mRNA expression of different specific markers corresponding to cancer-associated fibroblasts (CAF) (Acta2, coding alpha-SMA), endothelial cells (EC) (Pecam1, coding for CD31), and tumor-associated macrophages (TAM) (Adgre1, coding for F4/80)." (PMID 32438553, 2020). "Moreover, the expression level of ACTA2 was significantly associated with poor prognosis, revealing again a close relationship between mesenchymal features, NCSC signature enrichment and tumor aggressiveness." (PMID 29163787, 2017). "However, ACTA2-positive cells were disoriented and/or enriched in the tumor foci." (PMID 27344183, 2016). "We then performed a correlation analysis between ACTA2 and FAP with the cfRNA‐defined subtype markers in tumor gene expression data from the COMPASS trial." (PMID 39478658, 2025). "Canonical markers were used to annotate different cell types: malignant cells (COL1A1, IBSP), myeloid cells (CD74, CD14), osteoclasts (CTSK, MMP9), pericytes (RGS5, ACTA2), endothelial cells (PECAM1, VWF), and tumor-infiltrating lymphocytes (CD3D, NKG7)." (PMID 40730548, 2025). "COL1A1 serves as a classical marker for normal fibroblasts, while ACTA2 is a common CAF marker, typically employed to identify activated fibroblasts actively shaping the tumor microenvironment." (PMID 41584584, 2025). "The findings indicated that the expression of ACTA2 and MYH11 in tumor samples of both datasets was significantly lower than that in normal samples, and the low expression of MYH11 in tumor samples was more significant." (PMID 40918458, 2025). "The corresponding heatmap depicted the high-expression profiles of various cell types in marker genes such as KRT19, VWF, ACTA2, CD68, and TPSB2, effectively distinguishing immune, stromal, and tumor cell components." (PMID 41488617, 2025). "Tumor cells in the edge zone exhibited a decrease in E-cadherin and were surrounded by neutrophils (CD15) and CAFs (ACTA2)." (PMID 40657372, 2025). "To further generalize these findings, we assessed the correlation of AEBP1 expression with CAF markers (ACTA2, FAP, and PDGFRB) and representative collagen family genes across 32 TCGA tumor types." (PMID 41373631, 2025). "Analysis of TCGA database (accession number: phs000178) revealed increased PSI values for ACTA2, AREG, BRCA1, DDX5, MSH6, and PARP1 in tumor tissues compared to adjacent tissues." (PMID 39773744, 2025). "After treatment with CM from tumor cells, LX2 cells transformed from spindle shaped to radial, with increased protrusions, upregulated activation marker (ACTA2, COL1A1, DES) expression, and downregulated quiescence marker (RGS5) expression." (PMID 41214328, 2025).
tumor (continued). "On the other hand, in tumor matched 0923CAF after coculture with LK0923, the most evident changes were a significant decrease in both ACTA2 and POSTN and a strong increase of PDPN mRNA expression." (PMID 38822309, 2024). "The RGS5+ CAFs in our study (which we appointed a T cell-exclusion role from tumor nests) also expressed MYH11, ACTA2, and COL4A1." (PMID 39516494, 2024). "In vivo experiments demonstrated that ITGA5-EVs-148a significantly suppressed the tumor growth and the expression levels of ITGA5, PCNA, ACTA2, and FSP." (PMID 39099892, 2024). "Immunofluorescent staining for MMP1 and myofibroblasts marker α-smooth muscle actin (ACTA2) revealed that the immuno-colocalization of MMP1 (red) and ACTA2 (green) was detected in stroma and MMP1 protein was highly expressed around the tumor cells." (PMID 38320998, 2024). "CAFs can also secrete numerous cytokines, such as ACTA2, FBLN1, TAGLN, etc., remodeling the tumor extracellular matrix, thereby leading to tumor progression." (PMID 38755647, 2024). "We further confirmed that CD36 was mainly expressed in myoepithelial tumour cells in PA tissue by using Pan-Keratin (PCK), ACTA2 and CD36 multiple immunostainings." (PMID 37679344, 2023). "ICAF, with low ACTA2 expression and high IL6 secretion, can be activated by paracrine factors secreted from tumor cells." (PMID 36900272, 2023). "Analysis of paired samples with both FFPE tissues and fresh frozen tumors showed that transcript levels of ACTA2, TPM2, CALD1, and TAGLN were significantly and positively correlated with the stromal percentage of the tumor." (PMID 37296997, 2023). "In contrast, MYH11+αSMA+ CAFs expressing myosin heavy chain 11 (MYH11) gene, ACTA2, and intermediate levels of CD34 were localized as a single layer encapsulating the tumor nest and orchestrating T-cell exclusion." (PMID 37342322, 2023). "Single-cell RNAseq and clustering analysis of these tumours uncovered a significant downregulation of CAF markers, such as Acta2 and Pdgfrb, in the CAF component of ATF4 knockout mice." (PMID 36765657, 2023). "The mesenchymal markers ACTA2, CDH2, CDH11, and VIM are involved in proliferation, generation of stem-cell-like cells, and tumor progression." (PMID 37345150, 2023). "iCAF were able to produce high levels of IL-6, IL-11, leukemia inhibitory factor (LIF), and chemokines (CXCL1, CXCL2) while myCAF, detected closer to the tumor lesions, expressed high levels of α-SMA and ACTA2 genes, CTGF and COL1A1 (TGF-β-response genes)." (PMID 37342322, 2023). "The FAP mRNA levels showed a significant positive correlation with the ACTA2, COL11A1, TNC, and PDPN genes in PanCK(-) AOIs at EOCC tumor invasive margin." (PMID 37964075, 2023). "Notably, the expression levels of Acta2 (which encodes αSMA) and Pdgfrb (which encodes platelet-derived growth factor receptor-β), which are broadly reported as markers of CAFs4,6, were nearly absent in the tumours grown in Atf4Δ/Δ mice." (PMID 35654839, 2022). "CAFs are also found to have elevated ACTA2 and EGR2, promoting contractility and fibrosis within tumor tissue." (PMID 35757757, 2022). "KRT15 marked a subset of KRT14high tumor nests, LHX2 marked the nucleus of cells along the outer periphery of KRT14high tumor nests, and ACTA2 marked the outer periphery of KRT14low tumor nests." (PMID 35687691, 2022). "The cluster of patients with worse overall survival was characterised by high expression of lactate-related transporters as well as high ACTA2 and CAV1 expression in tumorous tissues." (PMID 35565415, 2022). "High expressions of tumor cell genes COL5A2 and ITGAV and non-tumor cell genes SPARC and ACTA2 are both positively correlated with poor overall survival and disease-free survival in MESO cohort." (PMID 35046456, 2022). "QRT-PCR showed that the expression of the ACTA2, C1QTNF9, DNAH8, GATM, LBP, and NGF were significantly downregulated in tumor samples." (PMID 36319832, 2022).
tumor (continued). "Tumor cells can be divided into 4 different subtypes, including basaloid cells (KRT5, KRT14), myoepithelial cells (ACTA2, MYL), cycling cells (MKI67, TOP2A) and duct-like cells (KRT7, KRT19)." (PMID 35860547, 2022). "We then calculated scores for SLS and IS within identified tumor spots using the most robust marker genes MGP (for SLS) and ACTA2 (for IS), and identified islands enriched with SLS (blue) or IS (green)." (PMID 36028490, 2022). "Some well-known marker genes were used to identify cell types, such as EPCAM and KRT19 for tumor cell, COL1A1 and ACTA2 for CAF, CD3D and CD3E for T cell, and CD68 and CD14 for macrophage." (PMID 36499343, 2022). "Meanwhile, a previous study showed that CAFs enhanced the tumor-initiating and tumorigenic properties of HCC cells, and ACTA2 was exactly a biomarker of CAFs." (PMID 36299502, 2022). "We also found that the ratio of myofibroblasts increases in tumor during SBA tumorigenesis, and the IHC staining of ACTA2, which is a well-known marker of myofibroblasts, confirmed the higher proportion of myofibroblasts in SBA tumor tissues." (PMID 36104333, 2022). "(2022) both identified a CAF subset expressing muscle cell related transcripts (i.e., ACTA2, TAGLN) which likely represent a subset of eCAFs that promotes tumor invasion." (PMID 35757757, 2022). "The WB showed that, compared to the control group, tumor tissues with stable overexpression of MIR99AHG had decreased expression of the TGF-β1, Vimentin, and ACTA2 and COL1A1." (PMID 36138468, 2022). "Smooth muscle actin 2 (ACTA2) and tyrosine kinase growth factor receptor (KDR) were identified as the hub genes, which were significantly downregulated in the tumor tissue of the two patients who responded to treatment." (PMID 34179721, 2021). "Tumor cells in metastases also strongly expressed the mesenchymal markers smooth muscle actin (SMA/ACTA2) and nuclear TWIST, while EPCAM expression was weaker compared with tumor cells in spheroids." (PMID 32533757, 2020). "A correlation was seen between high ACTA2/IL6 co-expression and the tumor grade (*P = 0.0179) and lymph node metastasis (*P = 0.0281)." (PMID 30744595, 2019). "Since gene expression patterns are derived from tumor lesions with mixed populations of cells, key CAF marker gene Acta2 expression was further examined using immunostaining." (PMID 29047229, 2018). "Tumor nodules were readily identifiable by Acta2 expression and H&E morphology, with non-hematopoietic components outlining the lung architecture (white arrows)." (PMID 40630529, 2025). "Additionally, canonical CAF markers ACTA2 and FAP exhibited elevated expression levels in tumor samples." (PMID 40771797, 2025). "Bmp5+ lobular-like fibroblasts and Cd36+ committed preadipocytes were not present within tumors, while Acta2 (α-SMA)+ myCAFs presented new tumor clusters not found in hyperplastic glands (Fig. EV5H,I)." (PMID 40216939, 2025). "Furthermore, spatial transcriptomics on human PDAC tissue revealed that iCAFs using gene markers IL6 and CXCL12 and myCAFs using gene markers ACTA2 and MMP11 were spatially distributed and correlate with tumor and immune cell localizations." (PMID 41376815, 2025). "The cell type-specific markers we used for cell annotation were as follows: T cell (CD3D); NK cell (KLRD1 and NKG7); plasma cell (IGKC and JCHAIN); Mast cell (KIT and TPSB2); tumour cell (CA9, NDUFA4L2 and SLC17A3); endothelium (PECAM1, PTPRB and KDR); mesangial cell (ACTA2 and PDGFRB)." (PMID 40830065, 2025). "Myoepithelial cells surround the ductal epithelium for structural support, and our results also showed that myoepithelial cell markers, including ACTA2, MYLK, and KRT14, were enriched in the perispatial domain of the tumor, suggesting high-quality detection of tumor contours using our algorithm." (PMID 39965034, 2025). "Notably, CAF surface markers ACTA2 and FAP are expressed by other cells within the tumor microenvironment, undermining the precision of CAF-based therapeutic strategies." (PMID 38818409, 2024).
tumor (continued). "In these human neoplasms, the macrophage signature correlated with the expression of SNA1, FN1, ACTA2 (αSMA), SPP1 (osteopontin), COL1A1, and VIM, all genes that are specific for active CAFs, indicating that this gene signature is associated with CAF activation." (PMID 37199012, 2023). "Furthermore, we also evaluated the expression of myofibroblast marker genes, such as COL1A2, COL3A1, ACTA2, and FAP, in the tumor microenvironment using an IHC assay." (PMID 37953225, 2023). "Increased expression of ACTA2, FLNA, TAGLN, and TPM1 may promote the transformation of macrophages into M2 in the tumor microenvironment." (PMID 37274283, 2023). "Similarly, non-tumor genes SPARC and ACTA2 expression correlated with overall survival in epithelioid subtype." (PMID 35046456, 2022). "Moreover, the expression of ACTA2, ASPN and COL11A1 genes are reduced in fibroblasts after cultivation with tumor cells." (PMID 36263012, 2022). "In addition, the ACTA2, ASPN, PDGFRB, PDPN, COL12A1, EMILIN1, and CDH11 genes were upregulated in CAFs of several tumor types." (PMID 36263012, 2022). "Non-tumor cell genes SPARC and ACTA2 expression correlated with overall survival in MESO cohort." (PMID 35046456, 2022). "Reports suggest that ACTA2 and FAP may characterize somewhat overlapping but distinct CAF subpopulations in several tumor types." (PMID 35805064, 2022). "IHC revealed expression of Sox1, Sox9, Map2, Acta2, Bglap and Afp in sections, indicating the presence various types of neural and non-neural tissues or cells in tumor." (PMID 33468253, 2021). "Moreover, genes representing mesodermal or/and endodermal tissue differentiation (ACP5, ACTA2, BGLAP, CTSK, DESMIN, FOXA2) were activated in tumor." (PMID 33468253, 2021). "Moreover, co-expression was found between CALD1, ACTA2 and CD206 in the tumor stroma, especially in patients with advanced BLCA." (PMID 34051818, 2021). "In an opposite manner, mRNA levels of some EMT markers such as Mmp2, Cdh2, and Acta2 are virtually absent in the ascites tumor cells." (PMID 34737944, 2021). "The expression of ACTA2 may stimulate the release of IL‐6 by CAFs to induce EMT and promote the progression of tumor phenotype from noninvasive to invasive phenotype." (PMID 32786144, 2020). "The heterogeneity of CAFs has been confirmed by numerous studies; in particular, FAP or ACTA2 (aSMA) up-regulation was demonstrated not to occur for all CAF populations within a single tumor." (PMID 33143259, 2020). "IL32 was independently and positively associated with Ki67, HIF1A, and ACTA2 and negatively with TJP1 in tumors and with IL10Ra and BCLxL in non-transformed tumor-adjacent tissue." (PMID 33020452, 2020). "The ACTA2+ area was quantified in SmoM2;PB-MYC mice and PB-MYC littermates (n=6 mice, 44-45 weeks), as well as their non-tumor littermate controls, Gli1CreER/+;R26LSL-SmoM2-YFP/+ (SmoM2) (n=5 mice, 45 weeks) and R26LSL-SmoM2-YFP/+ (WT) (n=3 mice, 45 weeks) mice." (PMID 27935821, 2017). "Interestingly, expression levels of ACTA2, S100A10 and VIM were positively and significantly correlated to tumor size, suggesting a relationship between NC derived stromal component and tumor growth." (PMID 29163787, 2017). "In bulk tumor‐derived expression data, we found a very strong correlation of SPOCK1 expression with markers of activated stroma: secreted protein acidic and cysteine rich (SPARC), α‐smooth muscle actin (αSMA/ACTA2), and fibroblast activation protein." (PMID 28486750, 2017). "As expected, NB5t primary cells showed increased expression of mesenchymal genes (NT5E, ENG, ACTA2, MME, CD44, VIM or ALPL), while NB5t tumor sample expressed mostly neuronal genes (TH, ENO2, NCAM1, DDC or CHGB) reflecting the neuroblastic phenotype of stage 4/M NB tumors." (PMID 29163787, 2017).
tumor (continued). "Consistent with this, we demonstrate that supplementation with NC derived stromal cells promotes proliferation and tumor aggressiveness in vivo, increasing expression of mesenchymal genes such as CD44, S100A10, ENG, VIM and ACTA2 (SMA), being the last one a typical marker of CAFs." (PMID 29163787, 2017). "Moreover, fluorescent IHC (F-IHC) analyses revealed a diminished intensity of staining for the stemness-related marker OCT4, alongside an intensified staining for markers indicative of differentiation (AFP, ACTA2 and CD57) in xenograft tumor tissues following SERPINB9 knockdown." (PMID 39528470, 2024). "Therefore, we further analyzed one SLS tumor and one IS tumor using Nanostring digital spatial profiler (DSP) to query spatial tumor microenvironment organization, and confirmed higher expression of the IS marker gene ACTA2 in IS-dominant tumors." (PMID 36028490, 2022). "In addition, IL-6 correlates with CAF marker ACTA2 and negatively correlates with tumor purity, suggesting that IL-6 is produced primarily by CAFs and not tumor cells." (PMID 30744595, 2019). "Interestingly, Acta2 and Cnn1 were decreased by 21- and 12-fold, respectively, in stromal Gli1-expressing tumor cells compared with WT, and VIM was not significantly altered." (PMID 27935821, 2017). "Through our immunohistochemical results, we could see that markers such as ACTA2, VIM, and MMP2 were mostly differentially expressed in the stromal area, including CAFs and vascular smooth muscle cells, but not in the tumor cells between the different risk score groups." (PMID 33747932, 2021). "Surprisingly, despite the absence of NOX4 in stromal cells, tumours from WT and NOX4-/- mice were identical in size and in the expression levels of Krt19, α-Sma (Acta2) and collagen 1 (Col1a1)." (PMID 40820091, 2025). "No positive correlations were observed for ACTA2, COL11A1, TNC, and PDPN genes in PanCK(-) AOIs at EOCC tumor center or at LOCC tumor invasive margin." (PMID 37964075, 2023). "On the other hand, expression of the myCAF markers Acta2 (α-SMA gene) and Transgelin (Tagln) in PSCs cocultured with tumor organoids was not affected by hypoxia." (PMID 36109493, 2022). "Likewise, when we explored the effects of IL1β-silenced tumor cells on co-cultured NCFs, we could observe that cocultured fibroblasts lost the expression of inflammatory cytokines, as IL6, LIF or CCL2, while acquired markers of myofibroblasts (ACTA2, PDPN, MYH11, or CNN1)." (PMID 34066976, 2021). "Although final tumor volume was not distinctly different between the vec-alone and ACTA2 shRNA-overexpressing mice, expression of PCNA was decreased in ACTA2-knockdown mouse tumors." (PMID 28881584, 2017). "ACTA2+ myoepithelial cells were found to be prominent in DCIS #2 ROI, less common in DCIS #1 ROI, and absent in the invasive ROI, invasive tumor cells were found within DCIS #2 ROI, and endothelial cells were found in slightly larger numbers within the invasive ROI." (PMID 38114474, 2023). "Interestingly, 5 existing markers (ACTA2, VIM, S100A4, POSTN, PDPN) are not specific for any of the 9 tumor types we studied." (PMID 36263012, 2022). "Notably, MED samples showed a similar epithelial cell content as in EBUS samples though with a stronger expression of markers of the tumor microenvironment (TME) (CDH5, PTPRC aka CD45, and ACTA-2) which, on the contrary, were absent in pure epithelial LNmets (EBUS samples)." (PMID 36587234, 2022).